SNHG22 (small nucleolar RNA host gene 22)
Synonyms: SCARNA17HG; U91; SCARNA17
Gene: Long non-coding RNA gene on chromosome 18 (49,813,944 to 49,851,059, forward strand). Ensembl gene ENSG00000267322.
Gene Ontology:
Biological process: RNA processing
Cellular component: Cajal body; nucleolus
Diseases named in the same sentence as SNHG22 in open-access papers:
SNHG22 is named in the same sentence as 10 diseases in open-access papers, as found by Europe PMC text mining. Sharing a sentence is not in itself a finding about the gene and the disease. The quoted sentences say what the papers report.
gastric cancer (4 papers, 2021 to 2025). A primary or metastatic malignant neoplasm involving the stomach. "For instance, the mechanism by which lncRNA small nucleolar RNA host gene 22 (SNHG22) promotes gastric cancer progression has been elucidated." (PMID 40042761, 2025). "Further, RNA pull-down using biotinylated SNHG22 and nuclear protein extracts from gastric cancer cells followed by mass spectrometry analysis of enriched proteins showed that SNHG22 directly interacts with EZH2." (PMID 38473229, 2024). "The lncRNA SNHG22 (small nucleolar RNA host gene 22) is highly expressed in gastric cancer cells and tissues and is correlated with poor prognosis in patients with gastric cancer." (PMID 38473229, 2024). "Here, we report that the expression of lncRNA SNHG22 (small nucleolar RNA host gene 22) was significantly increased in GC (Gastric Cancer) tissues and cells, which confers poor prognosis of patients." (PMID 34663788, 2021). "The expression levels of SNHG22 were analyzed using TCGA dataset by GEPIA and we found that SNHG22 was upregulated in gastric cancers compared with non-tumor tissues." (PMID 34663788, 2021).
breast carcinoma (2 papers, 2020 to 2022). "Intriguingly, SNHG22 had specific upregulation in TNBC cells whereas had no observable differential expression in other breast cancer types." (PMID 32565736, 2020). "Interestingly, it manifested that the expression of SNHG22 had no significant differentials between MCF-10A cells and hormone dependent breast cancer cell lines (MCF7 and T47D) or HER2-positive breast cancer cell lines (MDA-MB-453 and SKBR3)." (PMID 32565736, 2020).
ovarian carcinoma (2 papers, 2020 to 2025). A malignant neoplasm originating from the surface ovarian epithelium. "Small nucleolar RNA host gene 22 (SNHG22) is a novel lncRNA that has been identified as tumor-contributor in ovarian carcinoma." (PMID 32565736, 2020). "Energy supply is critical for tumor metastasis, and SNHG22 regulated by SP1 can promote glycolysis and the proliferation of cancer cells, thus facilitating the metastasis of ovarian cancer." (PMID 41200835, 2025).
colon cancer (1 paper, 2022). "In this study, some of the DEirlncRNAs in the process of modeling that have been already identified play an important role in malignant phenotypes of various cancer types, such as SNHG22, PRR7-AS1, and LINC00941, especially for colon cancer, while others were revealed for the first time." (PMID 35249533, 2022).
preeclampsia (1 paper, 2022). Preeclampsia is a hypertensive disorder of pregnancy that is characterized by new-onset hypertension with proteinuria presenting after 20 weeks of gestation, and depending on mild or severe forms may initially present with severe headache, visual disturbances, and hyperreflexia. "Long non-coding RNAs (LncRNAs) act as an indispensable role in the Preeclampsia (PE)-related trophoblast function, while its relationship with Small Nucleolar RNA Host Gene 22 (SNHG22) remains unknown." (PMID 35679761, 2022). "However, changes in SNHG22 in developed preeclampsia may just reflect the compensatory mechanisms the placenta undergoes in this condition but are not causative." (PMID 35679761, 2022).
prostate carcinoma (1 paper, 2022). A carcinoma that arises from epithelial cells of the prostate gland. "However, SNHG22 expression was not significant when compared between 52 pairs of prostate cancer tissue samples and adjacent normal tissues." (PMID 35864871, 2022).
cancer (5 papers, 2022 to 2023). A tumor composed of atypical neoplastic, often pleomorphic cells that invade other tissues. "To date, there are 22 members of the SNHG family (SNHG1 to SNHG22) many of which have been shown to be deregulated in cancer, being critically involved in processes such as cancer cell proliferation, tumor progression, metastasis, and chemoresistance." (PMID 36139687, 2022). "SNHG22 has been detected to be overexpressed and to act as an oncogene in multiple cancers, including CRC." (PMID 35350786, 2022). "Moreover, the lncRNA small nucleolar RNA host gene 22 (SNHG22) impacts cancer initiation and progression via the miR-2467/Gal-1 signaling pathway." (PMID 37322431, 2023).
tumor (5 papers, 2019 to 2025). "SNHG6 correlates with tumor stage and metastasis as a prognostic marker, and SNHG22 promotes cell proliferation and invasion through the miR-128-3p/E2F3 axis." (PMID 41301542, 2025). "SNHG22 was proved to be overexpressed in epithelial ovarian carcinoma and acts as an oncogene promoting tumor progression." (PMID 34663788, 2021). "Small nucleolar RNA host gene 22 (SNHG22) is a novel lncRNA which was discovered as highly expressed and as a tumor-promoter in epithelial ovarian carcinoma cells through the miR-2467/Gal-1 axis." (PMID 32565736, 2020). "Here, we demonstrated that the expression of SNHG22 was significantly increased in EOC tumor tissues." (PMID 31581131, 2019). "In addition, using RNA pull-down followed MS assay, we found that SNHG22 directly bound to EZH2 (enhancer of zeste 2 polycomb repressive complex 2 subunit) to suppress the expression of tumor suppressor genes." (PMID 34663788, 2021). "Further results of ChIP assays revealed that SNHG22 could recruit EZH2 to the promoter regions of multiple tumor suppressor genes (E-cadherin, EAF2, ADRB2, rap1GAP and RUNX3), and modulating H3K27me3 levels to repress their transcription." (PMID 34663788, 2021). "Together, these data indicated that SNHG22 promotes GC progression through elevating Notch1 and recruiting EZH2 to suppress tumor suppressive genes in vivo." (PMID 34663788, 2021). "In TNBC, SNHG22 drives tumor progression by sponging miR-324-3p and upregulating SUDS382; LRRC75A-AS1 (SNHG29) promotes tumor progression by targeting the miR-380-3p/BAALC pathway, and SNHG8 promotes tumor progression through the miR-335-5p/PYGO2 axis." (PMID 41301542, 2025).
SNHG22 also shares sentences with these, for which no sentence is quoted: endometriosis (1 paper); hepatocellular carcinoma (1).